NLRP3 (NLR family pyrin domain containing 3)
Diseases named in the same sentence as NLRP3 in open-access papers (continued):
Sharing a sentence is not in itself a finding about the gene and the disease.
aspergillosis (8 papers, 2014 to 2022). Aspergillosis is an infection, growth, or allergic response caused by the Aspergillus fungus. "To directly prove this, we assessed NLRP3-deficient mice for susceptibility to aspergillosis and the effects of IL-37 administration." (PMID 25375146, 2014). "Genotype difference in NLRP3 rs3806265 between the case and control groups was statistically significant (p = 0.0451) and the CC homozygote of rs3806265 was associated with a higher risk of aspergillosis (p = 0.0130; OR = 2.567, 95% CI: 1.239 to 5.255)." (PMID 35407478, 2022). "On the contrary, CC homozygote of rs3806265 in NLRP3 and TT homozygote of rs1684579 in NLRC5 was associated with a high risk of aspergillosis, especially of IPA." (PMID 35407478, 2022). "The CC homozygote of NLRP3 rs3806265, TT homozygote of NLRC5 rs1684579 and T allele of NLRC5 rs12598522 were associated with a higher risk of aspergillosis while TT homozygote of NLRC4 rs212704 was associated with a lower risk of aspergillosis." (PMID 35407478, 2022). "A total of 4 SNPs (NLRP3 rs3806265, NLRC4 rs212704, NLRC5 rs1684579, and rs12598522) were observed an association with aspergillosis risk." (PMID 35407478, 2022). "Our results identified the association of NLRP3, NLRC4, and NLRC5 genetic variation with the susceptibility of pulmonary aspergillosis for the first time." (PMID 35407478, 2022). "Our study demonstrated that the polymorphisms of NLRs (NLRP3, NLRC4, NLRC5) were associated with pulmonary aspergillosis risk, but there were still some limitations." (PMID 35407478, 2022). "In an aspergillosis mouse model, several kinds of NLRs increased in the infected lungs, including NLRP3, NLRC4, and NLRC5, but their exact functions remain to be explored." (PMID 35407478, 2022). "A total of eight SNPs (NLRP3 rs3806265, NLRC4 rs212704 and NLRC5 rs1684579, rs12598522, rs3995817, rs3995818, rs34531240, rs28438857) were observed an association with susceptibility of pulmonary aspergillosis." (PMID 35407478, 2022). "In lung aspergillosis mouse model, compared with untreated aspergillosis mice, expression of NLRP3 mRNA was significantly decreased in mice intraperitoneally injected with IL-37, while levels of myeloperoxidase (Mpo), CxCl2, IL-1β, IL-17A, and IFN-γ were significantly reduced." (PMID 29805973, 2018). "In an invasive pulmonary model of aspergillosis, NLRP3 and AIM2 were required to engage the inflammasome to trigger innate immune responses against A. fumigatus; mice lacking both AIM2 and NLRP3, but not mice lacking a single inflammasome receptor, were hyper susceptible to invasive aspergillosis." (PMID 28740491, 2017). "In addition, AIM2 and NLRP3 activity in both the hematopoietic and the stromal compartments is required to protect the host against aspergillosis." (PMID 26204108, 2015). "IL-37 markedly reduced NLRP3-dependent neutrophil recruitment and steady state mRNA levels of IL-1β production and mitigated lung inflammation and damage in a relevant clinical model, namely aspergillosis in mice with cystic fibrosis." (PMID 25375146, 2014). "For the first time, we found rs3806265 in NLRP3, rs212704 in NLRC4 and rs12598522, rs34531240, rs28438857, rs3995818, rs3995817, rs1684579 in NLRC5 were associated with pulmonary aspergillosis in non-neutropenic patients." (PMID 35407478, 2022). "The aim of this study was to investigate the relationship between NLRP3, NLRC4, and NLRC5 gene polymorphisms and susceptibility to pulmonary aspergillosis in non-neutropenic patients among the Chinese population." (PMID 35407478, 2022). "In this study, we investigated 16 SNPs in NLRP3, NLRC4, and NLRC5 genes among the southeastern Han Chinese population and analyzed the relationships between these SNPs and susceptibility of pulmonary aspergillosis in non-neutropenic patients." (PMID 35407478, 2022). "Mice lacking both AIM2 and NLRP3 were highly susceptible to aspergillosis, indicating that AIM2 might be co-activated with NLRP3." (PMID 35639503, 2022).
diabetic neuropathy (8 papers, 2016 to 2025). A chronic, pathological complication associated with diabetes mellitus, where nerve damages are incurred due to diabetic microvascular injury involving small blood vessels that supply these nerves, resulting in peripheral and/or autonomic nerve dysfunction. "Multiple processes are involved in the development and activation of the NLRP3 inflammasome in diabetic neuropathy including the Priming and the Activation step." (PMID 40205269, 2025). "Another study found that liraglutide decreased diabetic neuropathy-induced microglial cell activation in the cerebral cortex and thalamus of rats by reducing the expression of the NLR family pyrin domain containing 3 (NLRP3) protein in brain microglia." (PMID 38997662, 2024). "Evidence is mounting that NLRP3 activation is crucial to the development of diabetic neuropathy after nerve damage." (PMID 39062016, 2024). "The results showed that JMT reduced the levels of mRNA and NLRP3 protein; also, the expression of IL-1β and caspase-1 in the spinal cord of diabetic neuropathy decreased." (PMID 35655729, 2022). "The role of NLRP3 inflammasome-mediated pyroptosis in diabetic neuropathy has recently attracted increasing attention." (PMID 34803664, 2021). "To date, a handful of articles on the involvement of NLRP3 in some pathophysiological changes and clinical manifestations of diabetic neuropathy are found in the literature." (PMID 32751658, 2020). "Based on our findings, we suggest a new model for the activation of the NLRP3 inflammasome and development of diabetic neuropathy." (PMID 26881256, 2016). "Therefore, in this review, we systematically summarize the molecular mechanisms of flavonoids in regulating NLRP3 inflammasomes and their major role in diabetic neuropathy." (PMID 40205269, 2025). "NLRP3’s role in diabetic neuropathy has yet to be fully determined." (PMID 39062016, 2024). "Also, the expression of the NLRP3 gene in the diabetic neuropathy training group was significantly lower than that of the diabetic neuropathy group (P < 0.05)." (PMID 35655729, 2022). "Though suggesting a contribution of the TXNIP, PR2X4, and HMGB1/TLR4-NLRP3 signaling pathways, these studies do not provide conclusive evidence on the role of NLRP3 in diabetic neuropathy and need to be confirmed in larger controlled studies." (PMID 32751658, 2020).
encephalitis (8 papers, 2018 to 2025). An acute inflammatory process affecting the brain parenchyma. "IL-18 and NLRP3 in serum are positively associated with the mRS score during the acute phase of encephalitis, suggesting that the pathophysiology of NMDAR encephalitis may be significantly influenced by the NLRP3 inflammasome pathway." (PMID 40075143, 2025). "NLRP3 inflammasome is activated in microglia or macrophages in the central nervous system in case of meningitis or encephalitis." (PMID 30042341, 2018). "Overactivation of the NLRP3 signaling pathway was found to promote the inflammatory response and cognitive dysfunction in mice with NMDAR encephalitis." (PMID 40075143, 2025). "KCH can potentially reduce HSV-1-induced encephalitis by regulating HSV-1 infection and HSV-1 infection-induced inflammation through NLRP3 inflammasome regulation." (PMID 38001788, 2023). "The results showed that the expressions of cIAP-1, MCSF, CXCL13, and NLRP3 were higher in the anti-NMDAR encephalitis group than controls and the viral encephalitis group (p < 0.05)." (PMID 36389787, 2022). "There were positive correlations between CSF NLRP3 inflammasome and cytokines in anti-NMDAR encephalitis patients." (PMID 31214158, 2019). "In a model of encephalitis, HSV-1 infection led to decreased inflammation and lower mortality in mice lacking ASC and NLRP3, as opposed to the WT mice." (PMID 38590522, 2024). "Although NLRP3 can be activated in the periphery of DENV-infected patients, the role of the NLRP3 inflammasome in DENV encephalitis has not been reported." (PMID 38355571, 2024).
fibromyalgia (8 papers, 2017 to 2025). A chronic disorder of unknown etiology characterized by pain, stiffness, and tenderness in the muscles of neck, shoulders, back, hips, arms, and legs. "Although much remains to be discovered about the mechanistic causes of body-wide pain syndromes such as fibromyalgia, several studies have indicated a role for NLRP3 in fibromyalgia-associated pain, and NLRP3 was found to be upregulated in patients with fibromyalgia." (PMID 31244767, 2019). "In one study, fibromyalgia patients were randomized for 40 days to receive either 300 mg/day of CoQ10 (divided into three doses) or placebo to measure changes in NLRP3 gene expression and serum cytokine levels." (PMID 34239993, 2021). "Increased expression of NLRP3 and IL-1β was also found in blood of patients suffering from fibromyalgia, and treatment with coenzyme Q10 decreased both overexpression of NLRP3 as well serum IL-1β and IL-18 levels." (PMID 32973552, 2020). "Together these data suggest that inhibition of the P2X7 receptor to attenuate NLRP3 inflammasome activation may be a potential therapeutic approach for the treatment of fibromyalgia." (PMID 37106238, 2023). "Interestingly, in fibromyalgia patients, after ROS-mediated activation, NLRP3 promotes the production of pro-inflammatory cytokines." (PMID 28661421, 2017). "We initially investigated motor activity, morphological, ultrastructural and oxidative stress and inflammatory changes at skeletal muscle level to document the basis of fibromyalgia etiopathogenesis and we studied in detail the involvement of NLRP3 inflammosome in the model of this disease." (PMID 28661421, 2017). "The presence of ROS in fibromyalgia activates an inflammasome called NOD-like receptor family, pyrin domain containing 3 (NLRP3), which triggers the release of inflammatory cytokines, such as IL-1β and IL-18." (PMID 34239993, 2021).
gastric ulcer (8 papers, 2021 to 2025). An ulcerated lesion in the mucosal surface of the stomach. "The investigation into the HMGB1/NLRP3/NF-κB signaling pathway revealed significant alterations across the experimental groups, highlighting the inflammatory response associated with gastric ulceration and the therapeutic potential of OMP and OMP-NS." (PMID 40563542, 2025). "NLRP3 inflammasome is an intracellular complex associated with inflammatory response, which induces the production of mature IL-1β and triggers apoptosis through caspase-1 cleavage, playing an important role in the formation of gastric ulcer." (PMID 38807640, 2024). "Conversely, treatment with OMP or OMP-NS showed significant reductions in HMGB1, NLRP3, NF-κB, and proinflammatory cytokine levels, indicating potential in mitigating inflammation and promoting healing in gastric ulcers." (PMID 40563542, 2025). "WEA can alleviate gastric ulcer through the inhibition of nuclear migration of the critical inflammatory factor NF-κB P65 and the inactivation of the NF-κB/NLRP3 pathway." (PMID 35277113, 2022). "The mentioned findings denote that inhibition of the NLRP3/caspase-1 and NF-κB channels, at least partially, facilitates he ameliorative effects of PAE against gastric ulcer triggered by ethanol." (PMID 34975497, 2021).
helminth infection (8 papers, 2019 to 2024). "Although NLRP3 inflammasome activation seems to be important to host defences against helminth infections by regulating Th2 and Th17 responses, it can also cause uncontrolled inflammatory action that leads to liver immunopathology." (PMID 38623843, 2024). "Evidence suggests that Nlrp3 deletion enhances Ym1 expression and M2 macrophage activation following helminth infection, which is typically associated with type 2 inflammatory responses." (PMID 39405117, 2024). "Currently, there are too few studies to fully determine the role of NLRP3 or its activation mechanism, in the host response to helminth infections." (PMID 38623843, 2024). "Activation of the NLRP3 inflammasome plays a key role in helminth infections by provoking Th2 and Th17/inflammatory responses." (PMID 38623843, 2024). "Conversely, in helminth infection studies, activation of the NLRP3 inflammasome suppressed the host's protective immunity against gastrointestinal helminth disease." (PMID 36869360, 2023). "Compared with our findings, two recent reports showed that NLRP3 suppresses innate and adaptive Th2 immune responses in a model of helminth infection." (PMID 34220814, 2021). "Recently, it has been reported that transcription factor NLRP3 in CD4+ T cells acts as a key transcription factor in Th2 immune response, which is associated with protective immunity to helminth infection." (PMID 32976511, 2020). "The possible triggers for NLRP3 inflammasome activation in helminth infections include endogenous signals generated by inflammation and tissue damage, as well as helminth products themselves." (PMID 32571988, 2020). "Together, these data reveal that NLRP3 is required for the resolution of inflammation and the timely initiation of repair processes in the lung following injury by helminth infection." (PMID 31586037, 2019). "We previously found that the NLRP3 inflammasome played a major role in suppressing the adaptive type 2 immune response to intestinal helminth infection (in the cecum) with T. muris." (PMID 31586037, 2019). "That the NLRP3 inflammasome appears to play a dual role in host defences against helminth infection might be due to the complexity of the parasite’s life cycle." (PMID 38623843, 2024). "Hence, NLRP3 appears to be an important regulator in helminthic infections and consequently, helminth-induced infection models represent a valuable tool to explore the role of NLRP3 in immune-regulatory microenvironments." (PMID 38842647, 2024). "Outside of the field of helminth infection, rigid particulate matter, specifically of a crystalline nature, is well known to activate the NLRP3 inflammasome in macrophages and dendritic cells (DC) previously stimulated (primed) with Toll-like receptor (TLR) agonists (1, 2, 12, –, 24)." (PMID 32571988, 2020). "Thus, mice lacking NLRP3 have dysregulated type 2 gene expression in the lung following tissue injury caused by helminth infection and may have abnormal neutrophil chemotaxis and alveolar Mφ function." (PMID 31586037, 2019). "Notably, transcription factor NLRP3 (nod-like receptor (NLR) family, pyrin domain containing 3) in CD4+ T cells acts as a key transcription factor in Th2 immune response, which is involved in protective immunity to helminth infection." (PMID 32976511, 2020). "Thus far we have demonstrated that although type 2 immune responses were enhanced in the absence of NLRP3, lung inflammation persisted after resolution of helminth infection." (PMID 31586037, 2019).
Hydrocephalus (8 papers, 2021 to 2024). Hydrocephalus is an active distension of the ventricular system of the brain resulting from inadequate passage of CSF from its point of production within the cerebral ventricles to its point of absorption into the systemic circulation. "Microglia activation has been associated with both vasospasm and hydrocephalus and is closely regulated by the IL-6 pathway and NLRP3 inflammasome." (PMID 36114540, 2022). "Besides, NLRP3 had a high diagnostic efficacy for postoperative intracranial infections and hydrocephalus in patients, and it was also an independent risk factor influencing patients’ postoperative intracranial infection and hydrocephalus." (PMID 38643470, 2024). "Similarly, the AUC of the combination of serum NLRP3, MMP‐9 and IFN‐γ for the diagnosis of hydrocephalus was 0.957, and the diagnostic efficacy of the combination of the three for hydrocephalus was higher than the diagnostic efficacy of NLRP3, MMP‐9 or IFN‐γ alone." (PMID 38643470, 2024). "Serum NLRP3, MMP‐9 and IFN‐γ levels had high diagnostic efficacy in patients with postoperative intracranial infection and hydrocephalus, among which serum NLRP3 level played a major role." (PMID 38643470, 2024). "Serum levels of NLRP3, MMP‐9 and IFN‐γ were determined using ELISA kits, with their diagnostic efficacy on intracranial infections and hydrocephalus evaluated by receiver operating characteristic curve analysis." (PMID 38643470, 2024). "In our research, it was demonstrated that serum NLRP3 levels were significantly elevated in intracranial infections and hydrocephalus in post‐craniotomy patients." (PMID 38643470, 2024). "Overall, serum NLRP3, MMP‐9 and IFN‐γ levels had high diagnostic efficacy for postoperative intracranial infection and hydrocephalus in patients." (PMID 38643470, 2024). "Subsequently, we evaluated the diagnostic efficacy of serum NLRP3, MMP‐9 and IFN‐γ levels for postoperative intracranial infection and hydrocephalus in patients by the ROC curve analysis." (PMID 38643470, 2024). "In contrast, recent study reported that NLRP3 activity is increased in patients with delayed neurological injury or hydrocephalus by elevated caspase 1 in CSF." (PMID 35819747, 2023). "To further explore NLRP3’s contribution to hydrocephalus, we developed Nlrp3−/− rats and found that the Nlrp3−/− group had lower CSF secretion and lateral ventricular volumes than the control group did after ICH-IVH." (PMID 35729645, 2022). "The present study investigated the function and molecular mechanism of the NLRP3 inflammasome in the pathogenesis of hydrocephalus with the aim of discovering a new therapeutic target for hydrocephalus patients." (PMID 35729645, 2022). "Further studies will focus on what components in the blood contribute to NLRP3 inflammasome activation, blood–CSF barrier disruption and LD formation and the relationship between them and hydrocephalus." (PMID 35729645, 2022). "It has been suggested that NLRP3 activation in the choroid plexus contributes to hydrocephalus by upregulating CSF secretion." (PMID 35729645, 2022). "Combined, these results suggest that the NLRP3 inflammasome contributes to the pathogenesis of hydrocephalus after ICH-IVH." (PMID 35729645, 2022). "Based on these findings, we investigated the characteristics of the NLRP3 inflammasome and the choroid plexus and proved that NLRP3 contributes to hydrocephalus by increasing CSF secretion in the choroid plexus." (PMID 35729645, 2022). "We demonstrated that activation of the NLRP3 inflammasome contributed to hydrocephalus by mediating CSF hypersecretion in the choroid plexus after ICH-IVH." (PMID 35729645, 2022).